CDK4 (cyclin dependent kinase 4)
Diseases named in the same sentence as CDK4 in open-access papers (continued):
Sharing a sentence is not in itself a finding about the gene and the disease.
osteosarcoma (continued). "Certain subsets of osteosarcoma harbor a supernumerary ring and/or giant marker chromosomes with amplification of the 12q13–15 region, including the murine double-minute type 2 (MDM2) and cyclin-dependent kinase 4 (CDK4) genes." (PMID 35049602, 2021). "Interestingly, when low-grade central or parosteal osteosarcoma dedifferentiate into a high-grade sarcoma, they retain their MDM2/CDK4 amplification and overexpression." (PMID 33799733, 2021). "CDK4 and MDM2 are often co-amplified and overexpressed in osteosarcoma." (PMID 31741049, 2020). "Several molecular-driven therapeutic programs are ongoing (for example, e-SMART, NCT02813135; INFORM2, NCT03838042; and the MATCH Screening Trial, NCT03155620), including with drugs of potential interest in osteosarcoma (e-SMART, NCT02813135, CDK4/6 inhibitor arms), and results are eagerly awaited." (PMID 33659950, 2020). "To assess the mechanism through which the RB-E2F pathway is being deregulated in the osteosarcoma cell lines without RB1 mutations, we analyzed CDK4 and CDK6 gene expression." (PMID 30220967, 2018). "As the chromosome 12 CDK4/MDM2 co-amplicon is present in many different tumour types, it is conceivable that co-generation of drivers on chromosomes 5 and 17 can also be found in tumours other than osteosarcoma." (PMID 28643781, 2017). "Additionally, about 20–23% of primary osteosarcoma biopsies showed intact Rb protein but defective p16INK4A or CDK4/CDK6 overexpression, indicating that CDK4/CDK6 inhibition could benefit a subset of patients." (PMID 40563473, 2025). "After treatment with 50 μg/mL ALAPP, the levels of expression of Cdk4 and Akt1 were unchanged in MC3T3 osteoblasts, but compared with levels in untreated cells, the levels of CDK4 and AKT1 expression were downregulated by about 42% and 43%, respectively, in MG-63 osteosarcoma cells." (PMID 37551169, 2022). "Co-targeting of cyclin and FGF/FGFR alterations with the CDK4/6 inhibitor palbociclib and the FGFR inhibitor lenvatinib can be carried out safely, with responses seen in three of six patients, including ongoing benefit in a patient with refractory osteosarcoma who continues to do well at 52+ months." (PMID 36455506, 2022). "Furthermore, we demonstrate that the defective cell cycle regulation pathway caused by p16INK4A inactivation can be therapeutically exploited using the selective CDK4/CDK6 inhibitor palbociclib in both 2D and 3D in vitro culture models of osteosarcoma cell lines." (PMID 34921235, 2022). "The inhibitory effects of ML264 on osteosarcoma cells are likely mediated via inhibition of JAK2 and STAT3 phosphorylation, decrease in β‐catenin and Runx2 levels, down‐regulation of cyclin D1, cyclin E1, CDK4, N‐cadherin, vimentin, Snail and MMPs expression, and up‐regulation of E‐cadherin levels." (PMID 32285603, 2020). "ALAPP significantly downregulated the expression of HSP90, CDK4, and AKT1 expression in MG-63 osteosarcoma, but not in the osteoblasts." (PMID 37551169, 2022). "Without ALAPP treatment, the levels of CDK4 and AKT1 expression in MG-63 osteosarcoma cells were about 92.1% and 86% higher, respectively, than those of Cdk4 and Akt1 expression in MC3T3 osteoblasts." (PMID 37551169, 2022). "Case 2 also seemed to morphologically has low‐grade osteosarcoma features, although MDM2 and CDK4 were not expressed immunohistochemically." (PMID 34008925, 2021). "Of the osteosarcoma cell lines examined in this study, SaOS-2 harbors a deletion in the RB1 gene that leads to a non-functional truncated protein, SJSA-1 has CDK4 amplification, and U-2 OS is p16 null." (PMID 30220967, 2018).
osteosarcoma (continued). "The presence of ABC-like features in osteosarcoma may obscure accurate diagnosis, but markers such as MDM2, CDK4, and the lack of USP6 rearrangement can provide critical diagnostic clues." (PMID 40926903, 2025). "However, in MG-63 osteosarcoma cells, ALAPP failed to upregulate HSF1, and HSP90, CDK4, and AKT1 were downregulated to about the level seen in osteoblasts." (PMID 37551169, 2022).
neutropenia (96 papers, 2016 to 2025). A decrease in the number of neutrophils found in the blood. "Despite their clinical efficacy, CDK4/6 inhibitors frequently cause adverse events, most notably neutropenia, the leading dose-limiting toxicity." (PMID 40907238, 2025). "Abemaciclib is structurally distinct from palbociclib and ribociclib, with greater CDK4 selectivity, and less risk of hematologic adverse effects such as neutropenia." (PMID 40136358, 2025). "Multiple studies have indicated that CDK4/6 inhibitors are linked with an elevated risk of various hematologic adverse events, such as neutropenia, anemia, and thrombocytopenia." (PMID 41259313, 2025). "Elevated baseline NLR is associated with an increased risk of severe neutropenia and shorter progression-free survival in patients treated with CDK4/6 inhibitors." (PMID 40907238, 2025). "Neutropenia represents the most frequent adverse drug reaction associated with CDK4/6 inhibitor class agents." (PMID 41368578, 2025). "Even though these CDK4/6is are administered orally, the associated side effects, such as neutropenia, leukopenia, and corrected QT interval (QTc) prolongation, necessitate regular hospital appointments." (PMID 40315425, 2025). "Neutropenia associated with CDK4/6 inhibitors is different from chemotherapy-induced neutropenia in that it is rapidly reversible due to a cytostatic (as opposed to cytotoxic) effect on neutrophil precursors in the bone marrow." (PMID 40136358, 2025). "CDK4/6i combinations are associated with neutropenia, leukopenia, anemia, and diarrhea, with discontinuations due to AEs in up to 19% of patients." (PMID 39087959, 2024). "The primary adverse effects linked with CDK4/6 inhibitors include neutropenia, leukopenia, and fatigue, although acute kidney injury is rarely observed." (PMID 38915820, 2024). "In particular, CDK4/6 inhibitors were significantly associated with grade ≥3 AEs, such as neutropenia, anemia, leukopenia, thrombocytopenia, alanine aminotransferase (ALT), aspartate aminotransferase (AST), nausea, headache, and back pain." (PMID 39329126, 2024). "Treatments with these CDK6i are closely associated with the occurrence of neutropenia, due to the inhibition of CDK4/6 in hematopoietic progenitors." (PMID 38845697, 2024). "We analyzed some common adverse events in clinical, and the use of CDK4/6 inhibitors was also associated with a higher incidence of certain adverse events, particularly neutropenia and leukopenia." (PMID 39161906, 2024). "The body mass index (BMI) has been found to be associated with certain toxicities of CDK4/6i, with higher BMI was associated with a significant decrease in neutropenia." (PMID 39009505, 2024). "For example, the FDA-approved combinations of fulvestrant + CDK4/6 inhibitors can be associated with high grade hematologic toxicities such as neutropenia and leukopenia." (PMID 36869202, 2023). "Neutropenia shortly after RT and in the 2nd cycle after RT was associated with CDK4/6i dose reduction (p = 0.0007; OR 5.5; p = 0.0002, respectively), especially G3-G4 neutropenia (p < 0.0001; OR 25.2; p < 0.0001; OR 7.8)." (PMID 36765648, 2023). "Neutropenia represented the most frequent hematologic side effect of CDK4/6 inhibitors treatment; however, for only 5% of respondents neutropenia was a relevant cause of treatment discontinuation for the outcome." (PMID 37954071, 2023). "Most patients had at least one episode of neutropenia (79%) during the study, which was associated with CDK4/6i dose reduction (p = 0.04)." (PMID 36765648, 2023). "The risk of CDK4/6i dose reduction was correlated with neutropenia grade, RT performed within the first two CDK4/6i cycles, and more than one concurrent RT; a tendency was observed in concurrent bone irradiation." (PMID 36765648, 2023). "Multivariate analysis showed that ECOG 1 performance status and neutropenia in C2D1 (G3–4) increased the risk of CDK4/6i dose reduction with HR = 3.13 and HR = 16.11, respectively." (PMID 36765648, 2023).
neutropenia (continued). "Palbociclib and ribociclib most commonly cause neutropenia, while diarrhea is the most common adverse effect of abemaciclib, perhaps because of its greater affinity for CDK4 over CDK6." (PMID 37759823, 2023). "The neutropenia grade correlated with higher risk, and patients with severe neutropenia (G3–4) in C1D14 or C2D1 had a higher risk of CDK4/6i dose reduction (p < 0.0001; OR 9.1; p < 0.0001; OR 13.9, respectively)." (PMID 36765648, 2023). "Among CDK4/6 inhibitors, previous research studies indicated that abemaciclib was associated with a low rate of neutropenia and a high incidence of GI toxicity." (PMID 36091147, 2022). "Nevertheless, compared with ET alone regimens, CDK4/6 inhibitors plus ET regimens were also associated with increased risk of grade 3/4 AEs, including neutropenia, leukopenia, and diarrhea." (PMID 33048129, 2020). "A significant increase in cases of neutropenia, leukopenia, and diarrhea was associated with treatment with CDK4/6 inhibitors plus ET." (PMID 33048129, 2020). "The most common AEs were associated with CDK4/6i, with neutropenia leading." (PMID 39120877, 2024). "Therefore, selective degraders for CDK6 have a less toxic potential than CDK4/6i, with a consequent reduction in the occurrence of neutropenia that is highly associated with the use of this type of inhibitor." (PMID 38845697, 2024). "While most of CDK4/6 inhibitors were associated with an increased incidence of hematologic AEs such as neutropenia and leukopenia, our analysis indicates a more varied profile for non-hematologic AEs, such as Abemaciclib showing a notable increase in events like diarrhea." (PMID 38212842, 2024). "Indeed, biological mechanisms responsible for neutropenia caused by CDK4/6 inhibitors versus chemotherapy are different." (PMID 37954071, 2023). "Neutropenia was the strongest factor associated with CDK4/6i dose reduction." (PMID 36765648, 2023). "However, the neutropenia associated with CDK4/6 inhibitors is distinct from chemotherapy-induced neutropenia in that it is rapidly reversible, reflecting a cytostatic effect on neutrophil precursors in the bone marrow." (PMID 37759823, 2023). "It is common for CDK4/6 inhibitors to cause myelosuppression, especially neutropenia." (PMID 37366898, 2023). "However, on multivariate regression analysis, only ECOG 1 performance status and severe neutropenia at the beginning of the second cycle were found to be associated with a higher risk of CDK4/6i dose reduction." (PMID 36765648, 2023). "The major adverse reactions of CDK4/6 inhibitors are leukopenia and neutropenia, mainly caused by palbociclib and ribociclib, and for this reason, they are dosed with three weeks of treatment and one week of treatment discontinuation to recover neutrophil counts." (PMID 36765923, 2023). "In contrast to chemotherapy, CDK4/6 inhibitor-associated neutropenia is rapidly reversible, as CDK4/6 inhibitors induce cell-cycle arrest by decreasing the proliferation of hematopoietic stem cells, with resumed proliferation following a CDK4/6 dose reduction or interruption." (PMID 36765923, 2023). "Thus, this strategy exploits the cytostatic nature of neutropenia caused by CDK4/6 inhibition and is yet another advantage of the mechanisms targeting cell cycle arrest as opposed to traditional chemotherapy." (PMID 35323345, 2022). "Importantly, neutropenia induced by CDK4/6 inhibitors differs from chemotherapy‐associated neutropenia in several aspects, including underlying mechanisms, degree of toxicity, and time to recovery." (PMID 33677841, 2021). "Neutropenia, a common adverse event associated with CDK4/6 inhibitor therapy, may be associated with a lower risk of disease progression." (PMID 34590788, 2021). "Importantly, neutropenia induced by CDK4/6 inhibitors differs from chemotherapy‐associated neutropenia in several aspects, including grade of toxicity, underlying mechanisms, and time to recovery." (PMID 33677841, 2021).
neutropenia (continued). "However, the addition of the CDK4/6 inhibitors to the ET regimen was associated with a higher risk of grade 3/4 AEs, especially neutropenia, leukopenia, and diarrhea." (PMID 33048129, 2020). "Overall, higher discontinuation rates and neutropenia were reported for CDK4/6i in both subpopulations." (PMID 40896422, 2025). "In our study, 144 patients (58.3%) developed grade 3 or higher neutropenia within the first 28 days of starting CDK4/6i in combination with aromatase inhibitors." (PMID 39686815, 2025). "The PALLAS trial demonstrated a lower incidence of neutropenia with CDK4/6i and aromatase inhibitor as adjuvant treatment in patients with BMI ≥ 25 without affecting treatment efficacy." (PMID 39686815, 2025). "The most common side effects of CDK4/6 inhibitors include neutropenia, nausea, leukopenia, fatigue, and diarrhea." (PMID 41282629, 2025). "A second US study evaluating CDK4/6i monotherapy, found lower neutropenia rates in older patients (≥70 years) compared to younger patients (46.5% [n=73] vs. 56.3% [n=129], respectively)." (PMID 40896422, 2025). "One of the primary findings of our study was the consistent association between elevated baseline NLR and the development of severe neutropenia during CDK4/6 inhibitor therapy." (PMID 40907238, 2025). "In the DAWNA-1 study, in which dalpiciclib was combined with fulvestrant, the most frequently reported adverse effect was neutropenia, as well as other cyclin-dependent kinase 4 and 6 inhibitors." (PMID 40075608, 2025). "Grade ≥3 neutropenia, typically occurs within the first two cycles of treatment with CDK4/6 inhibitors, and it can be resolved by adjusting the dosage." (PMID 40104496, 2025). "Involving 188 patients, the study revealed no significant increase in grade ≥ 3 hematologic toxicities, such as anemia or neutropenia, among patients receiving both treatments compared to those treated with CDK4/6 inhibitors alone." (PMID 39941794, 2025). "All three CDK4/6 inhibitors showed high signal strength for hematologic and lymphatic disorders, including neutropenia, anemia, thrombocytopenia, and reduced red blood cell counts." (PMID 41259313, 2025). "The most common treatment-emergent adverse events for camizestrant 75 mg (phase III dose) plus each CDK4/6i were diarrhea [with abemaciclib (87.5%)] and neutropenia [with palbociclib (80%) and ribociclib (32.1% for 400 mg and 53.1% for 600 mg)]." (PMID 40788187, 2025). "As well as other cyclin-dependent kinase 4 and 6 inhibitors, the most common adverse effect was neutropenia, followed by leukopenia and anemia." (PMID 40075608, 2025). "The adverse reactions of CDK4/6 inhibitors primarily affect the hematological system, including Neutropenia and Leukopenia, followed by the digestive system." (PMID 40104496, 2025). "Palbociclib and ribociclib exhibit less specificity in inhibiting CDK4 compared to abemaciclib, correlating with heightened incidences of neutropenia." (PMID 38791919, 2024). "Almost half of the patients had CDK4/6i dose reduction (44%), mainly due to neutropenia (14 out of 15 patients with dose reduction)." (PMID 39120877, 2024). "Previous clinical trials reported low grade neutropenia after abemaciclib administration, compared to both approved CDK4/6 inhibitors palbociclib and ribociclib." (PMID 38986222, 2024). "Although this resulted in intermittent neutropenia (class effect of CDK4/6 inhibitors), the blood count otherwise normalized after a few months, with the known metastases also showing a response on PET/CT." (PMID 38329600, 2024). "The most commonly reported adverse events of CDK4/6 inhibitors include neutropenia, leukopenia, and diarrhea." (PMID 39199640, 2024). "Despite an increased incidence of grade ≥ 3 adverse events (AEs), such as neutropenia and asthenia, CDK4/6is present a markedly lower toxicity profile compared to traditional chemotherapy, with manageable side effects." (PMID 38791919, 2024).